RELL1 (RELT like 1)
Description:
Induces activation of MAPK14/p38 cascade, when overexpressed. Induces apoptosis, when overexpressed.
Tractability: Antibody: UniProt places it where antibodies can reach, with high confidence; its Gene Ontology location is reachable by antibodies, with high confidence; UniProt predicts a signal peptide or a membrane-spanning region; the Human Protein Atlas places it where antibodies can reach. PROTAC: ubiquitination databases record sites on it.
Gene: Protein-coding gene on chromosome 4 (37,590,800 to 37,686,413, reverse strand). Ensembl gene ENSG00000181826.
Subcellular location: Cell membrane
Subcellular location (Human Protein Atlas): Microtubules; Plasma membrane
Gene Ontology:
Molecular function: protein binding
Biological process: positive regulation of p38MAPK cascade
Cellular component: plasma membrane
Genetic constraint (gnomAD): Loss-of-function variants: 3 observed, 16.48 expected, observed/expected ratio (o/e) 0.18, 90% interval 0.082 to 0.47. The upper end of that interval is the gene's LOEUF score, 0.47, which puts it in group 2 of 6, group 1 being the genes least tolerant of losing a copy. Missense variants: 270 observed, 305.32 expected, observed/expected ratio (o/e) 0.88, 90% interval 0.8 to 0.98. Synonymous variants: 129 observed, 127.34 expected, observed/expected ratio (o/e) 1.01, 90% interval 0.88 to 1.17.
Homologues: Orthologues: chimpanzee RELL1 (100% identical), rabbit RELL1 (92% identical), pig RELL1 (92% identical), mouse Rell1 (88% identical), guinea pig RELL1 (87% identical), macaque RELL1 (83% identical), rat Rell1 (83% identical), dog RELL1 (70% identical), tropical clawed frog rell1 (53% identical), zebrafish rell1 (43% identical).
Diseases named in the same sentence as RELL1 in open-access papers:
RELL1 is named in the same sentence as 17 diseases in open-access papers, as found by Europe PMC text mining. Sharing a sentence is not in itself a finding about the gene and the disease. The quoted sentences say what the papers report.
colorectal cancer (2 papers, 2023 to 2024). A primary or metastatic malignant neoplasm that affects the colon or rectum. "RELL1 is associated with a ceRNA network and is considered one of several hub genes to be pro-tumorigenic in colorectal cancer." (PMID 37893069, 2023). "Bioinformatic analysis indicated that RELL1 contributed to the dysregulation of several genes in colorectal cancer by competing for miRNA molecules." (PMID 37893069, 2023). "Bioinformatic analysis indicates that RELL1 expression is a poor prognostic indicator for gliomas and may serve a pro-tumorigenic role in colorectal cancer." (PMID 39767574, 2024). "Thus far, reports of RELL1 indicate that it is an oncogene for glioma and a poor prognostic indicator for glioblastoma and colorectal cancer." (PMID 39767574, 2024).
glioblastoma (2 papers, 2023 to 2024). The most malignant astrocytic tumor (WHO grade IV). "In contrast to circRELL1, mutations in the RELL1 protein may be pro-tumorigenic for gastric cancer, as the N255D mutation described previously for glioblastoma was also expressed in at least 30% of gastrointestinal tract cancer patients." (PMID 37893069, 2023). "Finally, mutations in the RELL1 protein may be pro-tumorigenic for lung cancer, as the N255D mutation described previously for glioblastoma was also expressed in at least 30% of lung cancer patients." (PMID 37893069, 2023). "A separate study identified an intracellular N255D mutation of RELL1 exclusive to glioblastomas yet not normal astrocytes." (PMID 37893069, 2023). "In contrast to the upregulation of RELL1 in glioblastoma, bioinformatic analysis indicates that RELL2 is expressed at lower levels in glioblastoma multiforme (GBM) and low-grade gliomas (LGG) versus normal non-malignant tissues." (PMID 37893069, 2023).
glioma (2 papers, 2023 to 2024). A benign or malignant brain and spinal cord tumor that arises from glial cells (astrocytes, oligodendrocytes, ependymal cells). "RELL1 is upregulated in gliomas and is a poor prognostic indicator for survival, as bioinformatic analysis revealed that RELL1 is expressed more prominently in metastatic brain tumors that have a poor prognosis." (PMID 37893069, 2023).
lung carcinoma (2 papers, 2023 to 2024). "High amounts of RELL1 protein were expressed in the breast and lung cancer cell lines, although a significant amount of RELL1 protein was also expressed in 293 cells." (PMID 39767574, 2024).
adenoma (1 paper, 2025). A neoplasm arising from the epithelium. "For instance, VRK1 showed a consistent upregulation in tumor/adenoma tissue with respect to adjacent mucosa, while WDR78, LPAR1, and RELL1 (the top three downregulated circRNA host genes in our dataset) decreased." (PMID 39980011, 2025).
atherosclerosis (1 paper, 2022). A disease characterized by the build-up of fatty material and calcium deposition in the arterial wall resulting in partial or complete occlusion of the arterial lumen. "The mechanism by which circ-RELL1 promotes the development of atherosclerosis is achieved by a ceRNA regulating the miR-6873-3p/MyD88/NF-κB axis, while circ-ANRIL increases the number of inflammatory factors to promote atherosclerosis." (PMID 36393967, 2022).
breast carcinoma (1 paper, 2020). "And autoantibodies against proteins translated by the RELL1 gene are considered as underlying biomarkers for detecting early-stage breast cancer." (PMID 32617077, 2020).
gastric cancer (1 paper, 2023). A primary or metastatic malignant neoplasm involving the stomach. "The RELL1 gene is also transcribed to produce a circRNA that is secreted in exosomes and functions to inhibit the progression of gastric cancer." (PMID 37893069, 2023). "A distinct circRNA RELL1 molecule consisting of exons 4, 5, and 6 was identified that is secreted in exosomes and appears to be protective against gastric cancer." (PMID 37893069, 2023).
HCMV infection (1 paper, 2020). "Here, we found that intracellular level of RELL1 in Han-infected cells was lower than that in HanUL138del cells, suggesting that pUL138 may downregulate RELL1 expression during HCMV infection." (PMID 32481657, 2020). "The downregulation of RELL1 by pUL138 during HCMV infection may inhibit HCMV replication, thus favoring the establishment of latent infection." (PMID 32481657, 2020). "Among these proteins, STEAP3, BORCS7, FAM172A, RELL1, and WDR48 were further demonstrated to affect HCMV infection." (PMID 32481657, 2020). "During the late phase of HCMV infection, STEAP3, BORCS7, FAM172A, RELL1 and WDR48 were differentially expressed between Han- and HanUL138del-infected cells, and further functional studies indicated that all of these proteins could affect HCMV infection." (PMID 32481657, 2020).
rosacea (1 paper, 2026). A chronic erythematous skin disorder that affects the face. "Four key genes (ALDH1A1, COL17A1, RELL1, and ZNF404) were identified, with ALDH1A1 as a risk factor and the others as protective factors for rosacea." (PMID 42112773, 2026).
type 1 diabetes (1 paper, 2021). "Fine-mapping of all the suggestive loci with gene burden tests using WES analysis revealed CRYGB and RELL1 to be potentially associated with the phenotype in individuals with type 1 diabetes." (PMID 33947878, 2021).
cancer (2 papers, 2023 to 2024). A tumor composed of atypical neoplastic, often pleomorphic cells that invade other tissues. "In contrast, thus far, the few reports studying the relationship of RELL1 protein with cancer indicate it is pro-tumorigenic, and it is interesting to speculate whether this correlates with the decreased ability of RELL1 to induce death in 231 and 293 cells in comparison to other RELTfms." (PMID 39767574, 2024).
infection (1 paper, 2021). The state of being infected such as from the introduction of a foreign agent such as serum, vaccine, antigenic substance or organism. "The RELL1 gene locus contains multiple circRNAs, including circ_0001400, one of the most highly upregulated human circRNA upon infection." (PMID 34276603, 2021).
RELL1 also shares sentences with these, for which no sentence is quoted: Diabetes (2 papers); tumor (2); bacterial infections (1); latent infection (1).